FOXP3 (forkhead box P3)
Diseases named in the same sentence as FOXP3 in open-access papers (continued):
Sharing a sentence is not in itself a finding about the gene and the disease.
asthma (continued). "We tested whether asthma was significantly associated with normalized methylation at each CpG site studied for Foxp3 using an ANOVA model." (PMID 29317916, 2018). "In this study, we sought to identify some CpG sites in specific genes that could be associated with asthma regulation (Foxp3 and IL10) and to identify the different AAPs for which exposure prior to the blood draw is linked to methylation levels at these sites." (PMID 29317916, 2018). "FOXP3 expression in buccal epithelium has been demonstrated by others, and FOXP3 methylation in saliva has been linked previously to both exposure to pollution and asthma outcomes." (PMID 28630656, 2017). "Therefore, we here discuss the major findings concerning the FOXP3 gene in association studies for asthma and other allergic conditions." (PMID 27965764, 2015). "In addition, SHS and air pollution exposure, which have been associated with an increased prevalence and severity of asthma, were positively associated with hypermethylation and the decreased expression of FOXP3 in Tregs." (PMID 27965764, 2015). "Thus, host genetic factors that affect FOXP3 can determine differences in susceptibility to allergic diseases such as asthma." (PMID 27965764, 2015). "We hypothesized that functional impairment of Treg and Teff cells are due to epigenetic and molecular modifications in FOXP3 and IFNγ that are mechanistically linked to outcomes of asthma." (PMID 23226205, 2012). "Finally, IL-7R, a candidate gene from ECA21, directly interacts with FOXP3 which is a regulatory T-cell transcription factor implicated in the pathophysiology of human asthma." (PMID 21843342, 2011). "However, we hypothesized whether environmental factors affecting FOXP3 levels may indirectly affect asthma risk." (PMID 36981683, 2023). "To assess the influence of the environment on the development of asthma, we hypothesized that in our cohort, exposure to environmental factors is associated with asthma risk in children, and that FOXP3 levels vary with their incidence and are negatively correlated with developing asthma." (PMID 36981683, 2023). "It is well known that DNA hypermethylation in the 5′ region of FOXP3 is associated with higher exposure of diesel exhaust exposure, and furthermore children with DNA hypermethylation in FOXP3 are assumed to be at higher risk of asthma, persistent wheezing, and early transient wheezing." (PMID 34754417, 2021). "Considering the findings of the present study, we believe that the mechanism of action of LLLT involved in inhibiting the inflammatory process of asthma may be directly linked to the activation of subpopulations of regulatory T lymphocyte (Treg), characterized by expression of FoxP3 and CD25+." (PMID 31015955, 2019). "In addition, asthma was associated with higher differentially methylated regions of Foxp3 and IL10." (PMID 29317916, 2018). "Therefore, the impairment of FOXP3 function caused by genetic polymorphisms and/or epigenetic mechanisms may be involved in the etiology of asthma and other allergic diseases." (PMID 27965764, 2015). "We can thus infer that increased exposure to SHS and AAP leads to hypermethylation of IFN-γ in Teffs and Foxp3 in Tregs, leading to decreased expression of these genes, causing impaired function of Teffs and Tregs that therefore leads to increased severity and prevalence of asthma and allergies." (PMID 23009259, 2012). "Our findings challenge this paradigm by revealing that in an OVA-induced asthma model, Treg cells lose active Foxp3 expression within sites of established Th2-driven inflammation." (PMID 40568113, 2025). "In contrast, IFNG and FOXP3 were significantly upregulated in the control group, suggesting potential differential roles for these proteins in asthma development." (PMID 40309741, 2025).
asthma (continued). "Patients with severe asthma show reduced numbers of FOXP3+ Tregs in the bronchoalveolar fluid compared to healthy controls, and decreased levels of circulating Tregs with impaired migration to the lung epithelium." (PMID 40497455, 2025). "A relevant study confirmed that Lactobacillus plantarum-CQPC11 treatment exhibited excellent effects in alleviating OVA-induced asthma, such as by upregulating T-bet and Foxp3 mRNA levels and inhibiting GATA3 mRNA levels." (PMID 39796399, 2025). "Genes such as IL1B and CCL17 exhibited significantly upregulated expression in the patient group, while others, like IFNG and FOXP3, were markedly downregulated (p < 0.05), suggesting their potential roles in asthma pathogenesis." (PMID 40309741, 2025). "Common environmental pollutants (i.e. polycyclic aromatic hydrocarbons (PAHs), CO, NO2 and particulate matter (PM)) induce alterations in CpG methylation of the FOXP3 locus, impairing Treg activity and worsening the asthma phenotype." (PMID 40497455, 2025). "Whole-transcriptome sequencing identified key inflammatory genes, such as IL1B, CCL17, and MUC5AC, that were upregulated in asthma patients, while immune regulatory factors like FOXP3 and IFNG were higher in healthy controls." (PMID 40309741, 2025). "In asthma models, SCFAs like propionate and butyrate induce FoxP3, potentially reducing allergic airway inflammation." (PMID 39065238, 2024). "Foxp3+CD25+CD4+ regulatory T (Treg) cells have been discovered as another pivotal CD4+ T cell subset involved in the pathogenesis of asthma." (PMID 39598682, 2024). "On the other hand, shikonin alleviated the imbalance of Th1/Th2 and Th17/Treg by regulating IFN-γ/FOXP3 and IL-4/IL-17A in asthma mice." (PMID 39444792, 2024). "Other studies also showed that IL-10 secretion from the gastric mucosa was increased in children with HP infection, and NAP inhibited Th2 responses by activating FOXP3+Tregs in an asthma model." (PMID 39564136, 2024). "Intranasal administration of crocetin (100 μM/day, for 9-10 weeks) in OVA-induced asthma in mice, reduced the number of Treg cells and the levels of Foxp3 and TIPE2, indicating treatment properties of crocetin in asthma." (PMID 38419885, 2024). "The current study found that miR‐1470 expression levels in exosomes of mesenchymal stem cells (MSCs) increased the proportion of CD4+CD25+FOXP3+ cells in asthma patients." (PMID 38545812, 2024). "We expected that the expression of FOXP3 would be lower in asthma patients and that the data collected on exposure to environmental factors in these patients will also be significantly different in the mentioned groups." (PMID 36981683, 2023). "We assessed the predictive value of FOXP3 in detecting asthma by analyzing the ROC curve and its accompanying indices." (PMID 36981683, 2023). "In pediatric asthma, regulatory T cells and Foxp3 expression are decreased in bronchoalveolar lavage fluid (BALF), and their suppressive function is impaired." (PMID 38106504, 2023). "For S. mansoni and asthma, other studies have also reported that the presence of Foxp3+ Treg cells was necessary for the helminth-mediated suppression of AAI." (PMID 37788409, 2023). "The sensitivity of the asthma predictive test constructed on the basis of FOXP3 was 67%, specificity was 86%, and the accuracy was 76%." (PMID 36981683, 2023). "It was acknowledged that Foxp3 was able to bind with the promoter of TGF-β1 to decrease T cell expression in asthma, and Foxp3 was also expressed by tolerogenic DCs in the lung." (PMID 36582191, 2022). "On the other hand, the prevention of HDM-induced asthma occurs by altering the pulmonary cDC maturation and through the induction of RORγt+FoxP3+ Treg cells." (PMID 36685549, 2022). "To distinguish the effects of LF in the population of T cells in OVA-induced asthma, we used Foxp3, IL-4, INF-γ, and CD4 antibodies to evaluate the differentiation of T cells." (PMID 36430662, 2022).
asthma (continued). "Herein, the asthma mice presented drastic reduction of IL-10 secretion accompanied of lower expression of Foxp3 in lung." (PMID 36685604, 2022). "It was unique to the present case that cytotoxic T lymphocyte antigen 4 (CTLA-4) in CD4+ Forkhead box P3 (Foxp3) + T cells were upregulated in the early phase before the development of asthma attacks." (PMID 35029177, 2022). "In patients with asthma and other allergic diseases, the expression of FOXP3 is reduced as compared to that of healthy controls." (PMID 35757774, 2022). "In OVA-induced asthma model, Δpep27 immunization induces anti-inflammatory Treg transcription factor Foxp3, and represses allergic Th2 transcription factor (GATA-3)." (PMID 35484967, 2022). "Although the contribution of Tregs in asthma is not fully addressed, clinical improvement following allergen immunotherapy (AIT) for asthma suggested an association with the induction of IL-10-, IL-35- and TGF-β-producing Tregs and Foxp3+ Tregs." (PMID 35757774, 2022). "Increased expression of USP21 has been found in Treg cells of asthma patients; the imbalance of FOXP3 and GATA3 is an important cause of pathogenic alteration of Treg cells in asthma patients." (PMID 35846989, 2022). "SCFAs have been shown to induce the expression of transcription factor Foxp3 in T lymphocytes, leading to the induction of Tregs which in turn can drive the immune response towards tolerance and attenuate asthma." (PMID 35265071, 2022). "At the same time, there is a marked fall of gene expression for T-bet (7B) and Foxp3 (7C) in asthma group compared to the control group." (PMID 36685604, 2022). "This study showed that the inhibition of FOXP3 reduced the effects of miRNA-221-5p on Th17/Treg Ratio in asthma." (PMID 34863307, 2021). "The positive correlation between VD3 and Foxp3+Tregs in the airways was observed in a severe pediatric asthma cohort." (PMID 33954205, 2021). "In a similar manner, delivery of the dectin-1/TLR2 agonist curdlan, a bacterial cell wall exopolysaccharide, to asthmatic mice induces differentiation of IL-10-expressing, Maf+Foxp3− Treg (i.e., Tr1 cells), and thereby reverses the animal’s asthma phenotype." (PMID 33777019, 2021). "The administration of si-SOCS1 suppressed the protein expression of SOCS1 and RORγt and induced that of FOXP3 in in vitro model of asthma following anti-miRNA-221-5p, in comparison with anti-miRNA-221-5p group." (PMID 34863307, 2021). "Forkhead box p3 (Foxp3+) regulatory T cells (Treg cells), which have been shown to play an important role in asthma, and can suppress effector CD4+ T cell responses." (PMID 33806085, 2021). "It was previously reported that bvPLA2 had anti-inflammatory and analgesic effects in rodent models of Parkinson’s disease, asthma, neuropathic pain, and drug-induced liver and kidney injuries via modulation of Foxp3+ regulatory T cells." (PMID 33568685, 2021). "Significant roles of CD4+CD25+Foxp3+ Treg cells have previously been identified in asthma regulation." (PMID 33784348, 2021). "Regulatory T cells (Tregs) with transcription factor FOXP3 play an important role in immunotolerance induction in asthma." (PMID 34691038, 2021). "In conclusion, the present study suggests that the observed differences in the frequencies of allergen-responsive Foxp3 or IL-10 CD4 T cells are associated with the distinct susceptibility of A/J, BALB/c, and C57BL/6 mice to experimental asthma." (PMID 34924814, 2021). "CD4+CD25+FoxP3+Tregs have been confirmed to play a pivotal role in allergic diseases such as asthma, hay fever, and allergic rhinitis." (PMID 33954205, 2021). "For example, as suggested above, both DC-VitD/dex and DC10 secrete IL-10 and thereby induce Th2 cells to differentiate into CD25+Foxp3+ Treg which can fully reverse the asthma phenotype." (PMID 33777019, 2021).
asthma (continued). "Previous studies have shown that luteolin affects asthma via the induction of FOXP3+ and CD4+CD25+ Tregs or acts as an immunosuppressant mTOR inhibitor to increase the percentage of CD4+FOXP3+ Tregs posttransplantation." (PMID 33532509, 2021). "Various T cells have the potential to mediate targeted immunosuppression, but FOXP3+ Treg has emerged as a dominant cell type; they are involved in maintaining tolerance during asthma inflammation." (PMID 33267824, 2020). "Of clinical relevance, vaccination of allergic mice with act-A-iTreg-modified DCs protected against experimental asthma through the generation of Foxp3+ Treg cells." (PMID 33114551, 2020). "Oral Bifidobacterium breve MRx0004, a commensal strain isolated from a healthy person, reduced the immunopathology of peribronchiolar and perivascular, and increased lung CD4+FoxP3+ cells in a murine model of severe asthma." (PMID 32431609, 2020). "An experimental study showed that F. prausnitzii induces human colonic DCs to prime CD4+ and CD39+ expression secreting IL-10 and IL-27, which are known as molecules that play a key role in Foxp3+-Treg generation and regulate asthma." (PMID 33339172, 2020). "For example, intratracheal delivery of Foxp3 modRNA to the lung protects against asthma, and intramyocardial delivery of VEGF modRNA promotes vascular regeneration after MI." (PMID 31843959, 2020). "Corticosteroids have been shown to upregulate Foxp3 expression in asthma patients, in an attempt to restore the balance between effector T cells and Treg cells." (PMID 32411140, 2020). "Of clinical relevance, vaccination of allergic mice with act-A-iTreg-modified DCs conferred protection against experimental asthma through the generation of Foxp3+ Treg cells in a feed-forward immunoregulatory circuit." (PMID 33114551, 2020). "In this sense, it has been reported as an increase in asthma severity in parallel with FOXP3 hypermethylation in blood DNA and diminished Treg function in children exposed to diesel exhaust particles." (PMID 32210181, 2020). "In a mouse model of asthma, IL-6 trans-signaling rather supported Th2 cytokine production, whereas classic IL-6 signaling was needed for the development of FoxP3+ regulatory T cells in the lung." (PMID 31694340, 2019). "Upon treatment with corticosteroids and following Allergen Immunotherapy (AIT) the concentrations of the Treg cells and the expression of FoxP3 and IL-10 can be restored and clinical improvement of asthma achieved." (PMID 30967873, 2019). "These genes include asthma-related molecules ranging from pattern recognition receptors (e.g., Tlr7) to transcription factors (e.g., Foxp3)." (PMID 30677748, 2019). "We compared the percentages of sialyl LeX positive cells among FOXP3+ Treg cells between asthmatic children and healthy controls, and found that it was significantly lower in the asthma patients (p = 0.012)." (PMID 31222115, 2019). "On the contrary, the proportion of sialyl LeX positive FOXP3+CCR7+CCR4− Treg cells among CD4+ T cells was lower in moderate-to-severe asthma compared with healthy controls (post hoc p < 0.05)." (PMID 31222115, 2019). "When analyzed using multivariate linear regression with the covariates of asthma status, age, BMI, and sex, Tregs were inversely proportional to the average Foxp3 methylation of the CpG sites in the promoter site (p = .039)." (PMID 29317916, 2018). "The GTAT3/FOXP3 expression ratio in moderate asthma was significantly higher than severe form (P <0.04)." (PMID 30116273, 2018). "GATA3/FOXP3 ratio in PBMCs isolated from patients with asthma was significantly higher than that of healthy subjects (9.49±2.02 vs. 3.48±0.78, P<0.004)." (PMID 30116273, 2018). "Our results showed that resveratrol induces the repression of miR34a leading to over expression of FOXP3 as a possible mechanism of attenuation of allergy/asthma symptoms in mice." (PMID 30619345, 2018).
asthma (continued). "The GTAT3/FOXP3 expression ratio in PBMCs isolated from patients with moderate asthma (11.09 ± 2.50) was significantly higher than that of the patients with severe asthma (3.90 ± 1.22) and the healthy controls (3.48 ± 0.78), (P<0.04 and P <0.01, respectively)." (PMID 30116273, 2018). "The results of the current study also indicated that GATA3/FOXP3 expression ratio in patients with asthma was significantly higher than those of healthy individuals." (PMID 30116273, 2018). "The FOXP3 expression in PBMCs isolated from patients with asthma was also higher than that of the healthy subjects, but the difference was not significant (2.15±0.76 vs. 1.01±0.11, P=0.10)." (PMID 30116273, 2018). "The expression of FOXP3 in PBMCs isolated from patients with moderate asthma (2.33±0.90) was higher than that of the ones with severe asthma (1.12±0.33) as well as the healthy subjects, but the differences were not statistically significant." (PMID 30116273, 2018). "To the best of our knowledge, we report a novel finding that resveratrol improves asthma via its effect on FOXP3 expression in pulmonary infiltrating cell and its therapeutic effect is mediated by miR-34a inhibition." (PMID 30619345, 2018). "GTAT3/FOXP3 expression ratio in patients with moderate asthma was significantly higher than that of the ones with severe asthma." (PMID 30116273, 2018). "It appears that RORγt and Foxp3 expressions were closely related to the proportion of γδT17 and γδTreg cells in the lungs of mice with OVA-associated asthma." (PMID 29995107, 2018). "The serum levels of IL-4, the expression level of GATA3, and GATA3/FOXP3 ratio in patients with asthma were significantly higher than healthy subjects (P <0.002, P <0.001, and P <0.004, respectively)." (PMID 30116273, 2018). "Treg cells control not only pathogenic Th2 cells, but also its effect on Th1 cells and the reduction of FOXP3 had been demonstrated in patients with stable asthma." (PMID 28824424, 2017). "Treatment of animals with high and medium concentrations of the extract showed overexpression of anti-inflammatory cytokine (IFN-γ) in asthma and increased number of Treg (FOXP3) compared to untreated asthmatic animals." (PMID 28824424, 2017). "We previously reported that bvPLA2 can induce Foxp3-expressing CD4+ regulatory T cells (Tregs) in OVA-induced asthma and acute kidney injury model." (PMID 28218721, 2017). "Defective IL-10 expression has been associated with increased steroid resistance in children with severe asthma, and vitamin D enhances the frequency of both IL-10+ and Foxp3+ Treg cells in children with severe asthma." (PMID 28725641, 2017). "In the lung, the Foxp3 and T-bet mRNA levels from the asthma groups was significantly lower than that in the control groups, which was reversed by treating asthma mice with TT." (PMID 28769099, 2017). "The importance of neonatal pTregs in asthma prevention is based on the observation that the cytokines IL-4 and IL-6 inhibit FOXP3 expression in naive CD4+ T cells." (PMID 28589115, 2017). "Our results show that CD4+ CD25+ Foxp3+ T cell percentages were lower in the BALF of mice with asthma than in the BALF of control mice, illustrating that CD4+ CD25+ Foxp3+ Treg levels are diminished in the lungs of mice with asthma." (PMID 28729731, 2017). "In this study, we explored the therapeutic potential of adenovirus-mediated Foxp3 gene delivery in an asthma model." (PMID 27633092, 2016). "In parallel with the CKA-induced asthma model, we also evaluated the role of Foxp3 expression in models of OVA-induced asthma." (PMID 27633092, 2016). "In this context, we evaluated the functions of Foxp3 in ovalbumin- and cockroach-induced asthma models." (PMID 27633092, 2016). "Development of asthma also involves a key transcription factor modulating the activity of T regulatory cells; that is, Forkhead box transcription factor 3 (Foxp3)." (PMID 27293973, 2016).